ZFAND1 (zinc finger AN1-type containing 1)
Description:
Plays a role in the regulation of cytoplasmic stress granules (SGs) turnover. SGs are dynamic and transient cytoplasmic ribonucleoprotein assemblies important for cellular protein homeostasis when protein production is suspended after acute exogenous stress. Associates with SGs and is involved in the efficient and specific arsenite-induced clearance process of SGs through the recruitment of the ubiquitin-selective ATPase VCP and the 26S proteasome. This process requires both complexes for efficient degradation of damaged ubiquitinated SG proteins during recovery from arsenite stress, and hence avoiding aberrant cytoplasmic SGs degradation via autophagy.
Synonyms: FLJ14007
Tractability: PROTAC: ubiquitination databases record sites on it; its protein half-life has been measured.
Gene: Protein-coding gene on chromosome 8 (81,701,313 to 81,732,903, reverse strand). Ensembl gene ENSG00000104231.
Subcellular location: Cytoplasm, Stress granule
Subcellular location (Human Protein Atlas): Centrosome; Cytosol
Gene Ontology:
Molecular function: proteasome binding; protein binding; zinc ion binding
Biological process: cellular response to arsenite ion; cellular response to heat; cellular response to osmotic stress; cellular response to oxidative stress; positive regulation of intracellular protein transport; stress granule disassembly
Cellular component: cytoplasmic stress granule
Genetic constraint (gnomAD): Loss-of-function variants: 31 observed, 29.74 expected, observed/expected ratio (o/e) 1.04, 90% interval 0.78 to 1.41. The upper end of that interval is the gene's LOEUF score, 1.41, which puts it in group 5 of 6, group 1 being the genes least tolerant of losing a copy. Missense variants: 301 observed, 267.9 expected, observed/expected ratio (o/e) 1.12, 90% interval 1.02 to 1.24. Synonymous variants: 99 observed, 84.24 expected, observed/expected ratio (o/e) 1.18, 90% interval 1 to 1.39.
Homologues: Orthologues: chimpanzee ZFAND1 (99% identical), pig ZFAND1 (93% identical), macaque ZFAND1 (88% identical), dog ZFAND1 (84% identical), mouse Zfand1 (83% identical), tropical clawed frog zfand1 (69% identical), zebrafish zfand1 (61% identical), rat Zfand1 (55% identical). Paralogues in human: ZFAND2B (23% identical), ZFAND2A (15% identical).
Diseases named in the same sentence as ZFAND1 in open-access papers:
ZFAND1 is named in the same sentence as 4 diseases in open-access papers, as found by Europe PMC text mining. Sharing a sentence is not in itself a finding about the gene and the disease. The quoted sentences say what the papers report.
breast carcinoma (1 paper, 2022). "Of these twenty, three showed evidence of association with LoF variants for overall breast cancer (ZFAND1, TYRO3, TMEM206/PACC1), and a further six with breast cancer subtypes (DNAH11, PARP2, LAMC3, MTMR11, EPN3, SLC22A10)." (PMID 35884425, 2022). "We found nominal evidence of association with breast cancer overall for LoF variants in three genes (ZFAND1, TMEM206/PACC1, and TYRO3), with ER-negative breast cancer in two genes, DNAH11 and PARP2, and with ER-positive disease in four genes LAMC3, MTMR11, EPN3, and SLC22A10." (PMID 35884425, 2022). "Among these genes, ZFAND1, TYRO3, and TMEM206/PACC1 showed evidence of association with LoF variants for overall breast cancer." (PMID 35884425, 2022).
Tumor (2 papers, 2022). "Tumor subtype analyses of LoF variants revealed evidence of association for ZFAND1, TYRO3, DNAH11, and PARP2 with ER-negative breast cancer, with ZFAND1 showing the strongest association (OR = 2.96 (CI 95% 1.59–5.50), p-value = 6.37 × 10−4)." (PMID 35884425, 2022). "According to the expression levels and regression coefficients, the downregulated BAX, PWP2, SERTAD1, S1PR4, ZFAND1, NUDT13 and ZNF107 with HR < 1 were considered as tumor suppressors, whereas the MVD, BAD, CPNE7, CPNE7, UTP23 and ZNF124 upregulated with HR > 1 were regarded as oncogenes." (PMID 36685828, 2022).
cancer (1 paper, 2017). A tumor composed of atypical neoplastic, often pleomorphic cells that invade other tissues. "Several known cancer mutations were seen in unique samples (KRAS p.G12D, BRAF p.D594G, NF1 p.R1362*, and ZFAND1 p.R130*)." (PMID 28852190, 2017).
ZFAND1 also shares sentences with these, for which no sentence is quoted: copy number variation (1 paper).